LUCAT1 (lung cancer associated transcript 1)
Diseases named in the same sentence as LUCAT1 in open-access papers (continued):
Sharing a sentence is not in itself a finding about the gene and the disease.
renal carcinoma (continued). "The patients with renal cancer with lower expression of DOCK8-AS1 displayed worse OS, and the patients with renal cancer with higher expressions of SNHG17, RUSC1-AS1, LINC02609, and LUCAT1 displayed worse OS." (PMID 35118117, 2021). "To further support this conclusion, we examined the expression of Lucat1 expression in 45 renal cancer tissues and their corresponding noncancerous tissues from Union Hosptial and obtained the same result." (PMID 29371934, 2017).
triple-negative breast carcinoma (5 papers, 2019 to 2025). An invasive breast carcinoma which is negative for expression of estrogen receptor (ER), progesterone receptor (PR), and human epidermal growth factor receptor 2 (HER2). "Next, we interrogated the association of LUCAT1 and its ceRNA network composed of miRs and mRNAs with overall survival of triple-negative breast cancer patients." (PMID 39594666, 2024). "The LUCAT1/miR-5582-3p/TCF7L2 axis was observed in luminal cells, whereas the LUCAT1/ELAVL1/LIN28B/SOX2 axis occurred in triple-negative breast cancer and basal cell lines." (PMID 41181715, 2025).
lymph node metastasis (4 papers, 2019 to 2022). "The analysis of clinical data manifested that LUCAT1 expression was correlated with tumor grade, lymph node metastasis, and distant metastasis." (PMID 31399501, 2019). "Next, we summarized the clinicopathological characteristics of these patients, and the data demonstrated that patients with higher LUCAT1 expression showed a poorer histopathological grade and more lymph node metastasis than the patients with lower LUCAT1 expression." (PMID 33097685, 2020). "High expression of LUCAT1 was positively correlated with TNM stage, lymph node metastasis and unfavorable prognosis in patients with LUAD." (PMID 35646922, 2022).
chronic obstructive pulmonary disease (3 papers, 2021 to 2024). A chronic and progressive lung disorder characterized by the loss of elasticity of the bronchial tree and the air sacs, destruction of the air sacs wall, thickening of the bronchial wall, and mucous accumulation in the bronchial tree. "While LUCAT1 regulates NF-KB signaling in chronic obstructive pulmonary disease (COPD) or inflammatory bowel disease (IBD), its specific involvement in cancer-related NF-KB signaling remains unknown." (PMID 39594666, 2024).
Cirrhosis (3 papers, 2018 to 2024). A chronic disorder of the liver in which liver tissue becomes scarred and is partially replaced by regenerative nodules and fibrotic tissue resulting in loss of liver function. "To start understanding the roles of deregulated expression of these lncRNAs in HCC and cirrhosis, we evaluated the associations between LUCAT1 and CASC9 expression and clinical-pathological variables." (PMID 30416681, 2018). "Statistical analysis showed that LUCAT1 expression is highly associated with tumour size, metastasis and tumour node metastasis (TNM) stage but not sex, age, HBsAg, cirrhosis and tumour number." (PMID 30588744, 2019). "A trend towards a decrease of CASC9 and LUCAT1 was observed, starting from healthy liver, to cirrhosis without HCC, to cirrhosis complicated by HCC with LUCAT1 displaying a relevant down-regulation in cirrhosis complicated by HCC, in line with its possible contribution to hepatocarcinogenesis." (PMID 30416681, 2018). "Notably, a trend towards a decrease in CASC9 and LUCAT1 was observed from healthy liver to cirrhosis without HCC and to cirrhosis complicated by HCC, in line with its possible contribution to hepatocarcinogenesis." (PMID 38398157, 2024).
pancreatic cancer (3 papers, 2021). "The high expression of LUCAT1 enhances the pathogenesis of pancreatic cancer and promotes the proliferation and invasion of pancreatic cancer cells by inducing the phosphorylation of Akt and p38 MAPK." (PMID 34736453, 2021).
pancreatic ductal adenocarcinoma (3 papers, 2020 to 2022). An infiltrating adenocarcinoma that arises from the epithelial cells of the pancreas. "In abdominal aortic aneurysm and pancreatic ductal adenocarcinoma, LUCAT1 also shows regulatory effects on cell viability and apoptosis." (PMID 34414854, 2021).
papillary thyroid cancer (3 papers, 2019 to 2024). "Of note, LUCAT1 performs similar functions in other cancer types as LUCAT1 silencing significantly inhibits papillary thyroid cancer cell proliferation and invasion as well as induces apoptosis." (PMID 39594666, 2024).
tongue squamous cell carcinoma (3 papers, 2020 to 2025). A squamous cell carcinoma that arises from the tongue. "Based on our results, it is reasonable to conclude that LUCAT1 inhibits the MAPK signalling pathway in tongue squamous cell carcinoma." (PMID 32922538, 2020).
abdominal aortic aneurysm (2 papers, 2021 to 2022). Enlargement and ballooning of the vessel that supplies arterial blood to the abdomen, pelvis and legs. "LUCAT1 acts as a decoy for miR-199a-5p and promotes MYRF expression, and lncRNA LUCAT1/miR-199a-5p/MYRF regulates the proliferation and apoptosis of SMCs in abdominal aortic aneurysms." (PMID 36093159, 2022).
aneurysmal disease (2 papers, 2020 to 2022). "Only LUCAT1 (AUC = 0.654, 95%CI = 0.534‐0.775, p = 0.018) represented an ability to discriminate aneurysmal disease in patients' blood plasma." (PMID 32655720, 2020). "However, only LUCAT1 showed the ability to discriminate aneurysmal disease in patients' blood plasma (AUC = 0.654, 95%CI = 0.534‐0.775, p = 0.018)." (PMID 32655720, 2020).
bladder urothelial carcinoma (2 papers, 2017 to 2025). "LUCAT1 expression is associated with clinical pathological characteristics of bladder urothelial carcinoma patients." (PMID 40025525, 2025).
choroidal melanoma (2 papers, 2020). Malignant tumor of melanocytes of the choroid. "However, the contribution of lncRNA LUCAT1 to choroidal melanoma (CM) remains unexplored." (PMID 31968402, 2020).
chronic heart failure (2 papers, 2020 to 2021). "Decreased expression of LUCAT1 in the blood serum of chronic heart failure patients has been associated with poor prognosis and shows diagnostic potential in identifying diabetic patients with diabetic lung disease." (PMID 32655720, 2020). "Furthermore, LUCAT1 is downregulated in the patients with chronic heart failure, which ptovides an involvement between LUCAT1 and heart disease." (PMID 34414854, 2021). "In addition, silencing of LUCAT1 is approved in chronic heart failure, and it can function as a beneficial role in the development of heart failure by accommodating cell viability and apoptosis via miR-612, suggesting that LUCAT1 plays a promoting role in myocardial injury." (PMID 34414854, 2021).
COVID-19 (2 papers, 2022 to 2024). A disease caused by infection with severe acute respiratory syndrome coronavirus 2. "Importantly, however, LUCAT1 seems to contribute to the production of alarmins, associated with severe courses of COVID-19." (PMID 35998224, 2022). "We next deciphered the function of the uncharacterized lincRNA PIRAT in human monocytes and the reasons for its opposite regulation compared to LUCAT1 in COVID-19." (PMID 35998224, 2022). "Both datasets were reduced to mRNAs detected in both the THP1 CRISPRi and the scRNA-seq experiments; 50.8% of the mRNAs regulated in monocytes during COVID-19 were affected by LUCAT1 silencing." (PMID 35998224, 2022). "To study its role in COVID-19, we silenced LUCAT1 in THP1 monocytes using CRISPR-interference (CRISPRi), followed by RNA-seq analysis and compared the results to patient scRNA-seq data." (PMID 35998224, 2022). "To determine the reason for the opposite regulation of PIRAT and LUCAT1 during COVID-19, we compared the influence of both lincRNAs on genes regulated in CD14+ monocytes in patients." (PMID 35998224, 2022). "Taken together, our results suggest PIRAT and LUCAT1 to regulate largely discrete sets of genes in CD14+ monocytes during COVID-19, with LUCAT1 inhibiting STAT and promoting NF-κB target gene expression and PIRAT serving as a withdrawable inhibitor of PU.1-dependent programs." (PMID 35998224, 2022). "Up-regulation of LUCAT1 and down-regulation of PIRAT thus alters PU.1, NF-κB, and JAK-STAT–dependent gene-expression in favor of the production of mediators associated with severe COVID-19." (PMID 35998224, 2022). "Thus, LUCAT1 up-regulation during monocyte activation in COVID-19 likely restrains JAK-STAT signaling, in favor of NF-κB–dependent immunity." (PMID 35998224, 2022). "Thus, whereas MaIL1 could nurture COVID-19 pathogenesis, LUCAT1 might adopt a protective function, preventing excessive IFN-STAT-driven immune responses." (PMID 35998224, 2022). "Collectively, PIRAT down-regulation and LUCAT1 up-regulation in monocytes in this model fuels the expression of S100A8 and S100A9, which contribute to myeloid imbalances during severe COVID-19." (PMID 35998224, 2022). "To investigate the relevance of LUCAT1 in the context of SARS-CoV-2 infections, we compared mRNAs regulated twofold or greater (up or down) upon LUCAT1 knockdown in THP1 cells with mRNAs regulated twofold or greater (up or down) in classic and intermediate monocytes during COVID-19 (scRNA-seq data)." (PMID 35998224, 2022).
esophageal cancer (2 papers, 2021 to 2024). A primary or metastatic malignant neoplasm involving the esophagus. "First, we removed lncRNAs with longer than 4000 nucleotides and then eliminated the molecules that have already been studied in esophageal cancer such as H19, SNHG6, LUCAT1, HOXA11." (PMID 34659577, 2021).
head and neck cancer (2 papers, 2020 to 2022). A primary or metastatic malignant neoplasm affecting the head and neck. "In addition, the expression of LUCAT1 was significantly upregulated in head and neck cancer tissues compared to normal tissues in TCGA datasets." (PMID 32922538, 2020).
oral cancer (2 papers, 2020 to 2023). "LUCAT1 promotes cell invasion in several cancer types, including gastric, liver, and oral cancer cells, by modulating YWHAZ, Annexin A2, or PCNA." (PMID 36980216, 2023). "We further demonstrated that LUCAT1 promoted the proliferation of oral cancer cells by enhancing the activation of the mitogen protein kinase (MAPK) signalling pathway." (PMID 32922538, 2020). "Vitamin D inhibited MAPK signalling pathway activation by suppressing LUCAT1, which suppressed the proliferation of oral cancer." (PMID 32922538, 2020). "Our study suggested that VitD could suppress the progression of oral cancer, and LUCAT1 may be a potential tumour marker for the diagnosis and prognosis of OSCC." (PMID 32922538, 2020).
serous ovarian cancer (2 papers, 2017). "LUCAT1 was enhanced in cisplatin-resistant A2780-DR high-grade serous ovarian cancer cells." (PMID 29156779, 2017).
viral infection (2 papers, 2020 to 2025). "Here, the authors show that the human lncRNA LUCAT1 sequesters STAT1 to limit JAK/STAT signaling and the inflammatory response to viral infection or TLR stimulation in myeloid cells." (PMID 33311506, 2020). "Collectively, these results indicate that LUCAT1 is induced by multiple TLR ligands and viral infection in human monocytic cells." (PMID 33311506, 2020).
asthma (1 paper, 2023). "Finally, we revealed the infiltration ratio of different immune cells in asthma and found a correlation between LUCAT1, MIR222HG, CD300E, and IER2 with some immune cells." (PMID 37259023, 2023). "Finally, we investigated the association between the immune cell ratio and the expression of LUCAT1, MIR222HG, CD300E, and IER2 in patients with asthma to determine the biomarkers correlated with the immune cell ratio." (PMID 37259023, 2023). "LUCAT1 and MIR222HG may modulate ferroptosis in asthma by various mechanisms, thereby influencing asthma progression." (PMID 37259023, 2023). "In this study, we screened key asthma-related genes (LUCAT1, MIR222HG, CD300E, and IER2) and immune cell infiltration profiles through bioinformatic analysis, which could provide insights into the pathogenesis of asthma and new perspectives and approaches for asthma diagnosis and treatment." (PMID 37259023, 2023). "However, neither LUCAT1 nor MIR222HG has been studied in the context of asthma remains unknown." (PMID 37259023, 2023).
cardiomyopathy (1 paper, 2021). A disease of the heart muscle or myocardium proper. "There is more and more evidence that LUCAT1 is one of the genetic risk factors of cardiovascular diseases, including coronary heart disease and cardiomyopathy, which suggests that LUCAT1 may also be a potential genetic marker of AMI." (PMID 34414854, 2021).
cholangiocarcinoma (1 paper, 2025). A carcinoma that arises from the intrahepatic biliary tree (intrahepatic cholangiocarcinoma) or from the junction, or adjacent to the junction, of the right and left hepatic ducts (hilar cholangiocarcinoma). "Next, we explored the effects of LUCAT1 on cell proliferation and migration of the human cholangiocarcinoma cells QBC939 and HuCCT1." (PMID 40713875, 2025). "Elevated expression of LUCAT1 was observed in CHOL tumor tissues and human cholangiocarcinoma cells, correlating with tumor size, CA-19-9 levels, and TNM stage." (PMID 40713875, 2025). "Moreover, we found that the proliferation and migration of the human cholangiocarcinoma cell line QBC939 and HuCCT1 were suppressed by silencing LUCAT1." (PMID 40713875, 2025).
coronary atherosclerosis (1 paper, 2025). Atherosclerosis of the coronary vasculature. "According to the authors, during the progression of human coronary atherosclerosis there is a dynamic disruption of the autophagy landscape, which could be protected by the lncRNA LUCAT1/hsa-miR-6776-5p/LRRC25-driven mechanism of autophagy activation." (PMID 40283676, 2025).
diabetic nephropathy (1 paper, 2020). "In further studies, we will analyze the function of LUCAT1 in an animal model of diabetic nephropathy and LUCAT1 expression profile in the clinical specimens of patients with diabetic nephropathy." (PMID 33426083, 2020). "Owing to the important role of EMT in diabetic nephropathy, we hypothesized that LUCAT1 may play a role in diabetic nephropathy." (PMID 33426083, 2020). "However, we did not explore the connection between LUCAT1 and diabetic nephropathy." (PMID 33426083, 2020).
endothelial dysfunction (1 paper, 2021). In vascular diseases, endothelial dysfunction is a systemic pathological state of the endothelium (the inner lining of blood vessels) and can be broadly defined as an imbalance between vasodilating and vasoconstricting substances produced by (or acting on) the endothelium. "Altogether, the results suggest that LUCAT1 plays a critical role in e-cig-induced endothelial dysfunction." (PMID 34863290, 2021). "Further, we investigated the functional effects of knocking down lncRNA LUCAT1, which was significantly upregulated after EAE treatment, on EC phenotypes in order to characterize its role in e-cig-induced endothelial dysfunction." (PMID 34863290, 2021).
glioblastoma (1 paper, 2025). The most malignant astrocytic tumor (WHO grade IV). "In glioblastoma stem-like cells (GSCs), LUCAT1 was found to be induced by nuclear factor erythroid 2-related factor 2 (NRF2) and hypoxia-inducible factor 1- α (HIF1α)." (PMID 39940704, 2025). "LUCAT1 was found to be highly expressed in the hypoxic regions of glioblastoma (GBM)." (PMID 39940704, 2025).
Hepatitis (1 paper, 2022). Inflammation of the liver. "In addition, most of these genes have a risk coefficient greater than 0 (AC008271.1, C11orf53, F2RL2, GBP5, LUCAT1, RP11‐149I23.3, RP11‐383 J24.1 and SLC35G2), except for CASP8 and RP11‐114B7.6, suggesting that these genes are adverse prognostic factors in hepatitis‐positive HCC patients." (PMID 35637633, 2022).
ischemic stroke (1 paper, 2021). A stroke disorder caused by obstruction of blood flow to the brain, due to thrombotic (local blood clot formation) or embolic (due to a blood clot or other material traveling from another site) event. "Regulatory axis, such as SND1-IT1/NAPA-AS1/LINC01001-miR-24-3p-LPAR3/ADORA1 and LUCAT1/ASAP1-IT2-miR-93-3p-GPR17 may play important roles in the progression of ischemic stroke." (PMID 34483854, 2021). "lncRNA-miRNA-mRNA regulatory axis such as SND1-IT1/NAPA-AS1/LINC01001-miR-24-3p-LPAR3/ADORA1 and LUCAT1/ASAP1-IT2-miR-93-3p-GPR17 may play important roles in the progression of ischemic stroke." (PMID 34483854, 2021).
laryngeal squamous cell carcinoma (1 paper, 2022). A squamous cell carcinoma that arises from the larynx. "It has been reported that LUCAT1 regulates MMP9 in Laryngeal squamous cell carcinoma cell lines, but its role in endometrial stromal cells remains to be studied." (PMID 35501804, 2022).
Obesity (1 paper, 2024). Accumulation of substantial excess body fat. "Of note, in both NW and CRC-affected subjects, DHA down-regulates LUCAT1, known for its oncogenic activity and previously found to be up-regulated in obesity." (PMID 38542331, 2024).
rheumatoid arthritis (1 paper, 2022). A chronic, systemic autoimmune disorder characterized by inflammation in the synovial membranes and articular surfaces. "These mRNAs were associated with pathway terms, such as “rheumatoid arthritis,” “immune system,” or “NF-κB signaling”, indicating a broad influence of LUCAT1 on peripheral immunity during infection." (PMID 35998224, 2022).
small cell lung carcinoma (1 paper, 2021). Small cell lung cancer (SCLC) is a highly aggressive malignant neoplasm, accounting for 10-15% of lung cancer cases, characterized byrapid growth, and early metastasis. "For example, Sun et al33 indicated that LUCAT1 expression was overexpressed in non–small cell lung cancer tissues and LUCAT1 knockdown suppressed the cell growth in vitro and in vivo." (PMID 33787082, 2021).
urothelial carcinoma (1 paper, 2025). A malignant neoplasm derived from the transitional epithelium of the urinary tract (urinary bladder, ureter, urethra, or renal pelvis). "To investigate the clinical relevance of LUCAT1 in BC, we determined the expression level of LUCAT1 in a total of 106 patients with urothelial carcinoma." (PMID 40025525, 2025).